NF1 (neurofibromin 1)
Diseases named in the same sentence as NF1 in open-access papers (continued):
Sharing a sentence is not in itself a finding about the gene and the disease.
congenital heart disease (5 papers, 2019 to 2024). A heart disease that is present at birth. "Of note, Nf1 is also associated with cardiovascular phenotypes, including systemic and pulmonary hypertension and congenital heart disease." (PMID 37760547, 2023). "Pulmonic stenosis is the most frequently reported congenital heart disease in NF1 and is almost always found in association with Noonan-like features, as it is the case in our NF1-deleted group (n = 2/2 patients with pulmonic stenosis and dysmorphic features)." (PMID 34199217, 2021). "Consistent with the literature, patients with WGD were observed to have a higher prevalence of CHD (21.4%) compared with patients with intragenic mutations (12.3%), confirming that heart defects are more common in these patients than in the general NF1 population." (PMID 31487937, 2019). "Indeed, they frequently exhibit dysmorphic features, overgrowth/tall-for-age stature, significant delay in cognitive development, congenital heart disease (CHD), and a greater number of cutaneous, subcutaneous, and plexiform NFs as compared to the general NF1 population." (PMID 31487937, 2019).
dementia (5 papers, 2012 to 2024). Loss of intellectual abilities interfering with an individual's social and occupational functions. "The relative rate of death caused by dementia was 2.42 (95% CI 0.90–6.47) in NF1 compared to controls with dementia or Alzheimer disease." (PMID 34257422, 2021). "The mean age at the first dementia-related diagnosis or drug purchase was slightly although not statistically significantly lower among individuals with NF1 than among controls, which is concordant with the idea of NF1-associated predisposition to dementia." (PMID 34257422, 2021). "Interestingly, non-disease-associated polymorphisms in the LRD region of the NF1 gene may increase the risk of an IBMPFD patient developing dementia." (PMID 32858845, 2020). "Totals of 16 and 165 individuals with at least two dementia-related diagnoses or drug purchases were identified in the NF1 and control cohorts, respectively." (PMID 34257422, 2021). "The hazard ratio for dementia in NF1 was 1.67 (95% confidence interval [CI] 1.00–2.80, P = 0.050)." (PMID 34257422, 2021).
embryonal rhabdomyosarcoma (5 papers, 2011 to 2025). A poorly circumscribed morphologic variant of rhabdomyosarcoma. "This study describes a new model of embryonal rhabdomyosarcoma driven by the loss of Nf1 and Ink4a/Arf, two mutations commonly found in patient tumors." (PMID 36826025, 2023).
ependymoma (5 papers, 2018 to 2025). A WHO grade II, slow growing tumor of children and young adults, usually located intraventricularly. "However, the nonsense NF1 variant was found in a patient for whom DNA methylation profiling amended the ependymoma diagnosis to RGNT." (PMID 36008825, 2022). "Pathogenic NF1 germline variants are extremely rare among children with ependymoma." (PMID 36008825, 2022). "We observed recurrent indel and nonsense NF1 mutations in classic ependymomas (38.9%)." (PMID 31822682, 2019). "Based on the described meta-analysis, the current best estimate of germline predisposition in childhood ependymoma suggests that 3.4% (7/207) carry a causative pathogenic germline variant, mainly located in NF2 and NF1." (PMID 36008825, 2022). "Both pLoF variants already known to cause ependymoma (in NF2 and NF1), were rediscovered." (PMID 36008825, 2022). "This may have inflated the reported NF1 carrier rate in patients with ependymoma." (PMID 36008825, 2022).
glaucoma (5 papers, 2015 to 2025). Increased pressure in the eyeball due to obstruction of the outflow of aqueous humor. "This is especially true in a newborn with unilateral glaucoma and orbital malformations, and the possibility of associated NF1 should be considered." (PMID 26514695, 2015). "Additionally, due to this being a single case with a short follow-up duration, the relationship between corneal opacity and NF1-associated glaucoma needs further study to prove." (PMID 39669368, 2024). "From 21 glaucoma disease-associated genes with measurable expression, 2 were upregulated (MYOC and FOXE3) and five were downregulated (SH3PXD2B, NF1, SBF2, ADAMTS17, and FOXC1)." (PMID 35348588, 2022). "Unlike the typical NF1 phenotype, which rarely included glaucoma, this patient exhibited extensive peripheral anterior synechiae in all quadrants with ectropion uveae, as well as a markedly increased axial length, resulting in significant anisometropia." (PMID 41341331, 2025). "The child had no familial history of glaucoma but the familial history of NF1 from her father which was confirmed through genetic examination." (PMID 39669368, 2024).
glomus tumor (5 papers, 2015 to 2024). A rare benign or malignant mesenchymal neoplasm arising from cells that resemble the modified smooth muscle cells of the glomus body. "Somatic and germline mutation analysis of NF1-associated glomus tumors showed inactivation of both NF1 alleles within the alpha-smooth muscle, actin-positive glomus cells." (PMID 37345107, 2023). "Taken together, the data indicate an effect of NF1 inactivation on the MAPK pathway in NF1-associated glomus tumor-derived glomus cells." (PMID 30336779, 2018). "The present case, with two glomus tumors successfully excised, indicates, together with a few previously reported cases, that there is an association between glomus tumors and NF1." (PMID 30336779, 2018). "In general, NF1-associated glomus tumors share many histologic similarities to sporadic ones: namely the cuboidal cells surrounding blood vessels, smooth muscle actin (SMA) positivity, and benign appearing rounded nuclei with moderate to abundant cytoplasm." (PMID 25674553, 2015). "In addition to its innocuous hallmark skin findings, including café-au-lait macules, axillary and inguinal freckling, and benign CNs, glomus tumors represent a less-recognized association of NF1." (PMID 37345107, 2023). "In these cells, there was increased activation of the Ras-MAPK pathway, suggesting that the pathogenesis of glomus tumors in NF1 may be due, in part, to the post-transcriptional loss of neurofibromin function." (PMID 37345107, 2023). "However, in a patient with NF1, the risk of glomus tumors is increased." (PMID 30336779, 2018). "However, the association of glomus tumors of the fingers with NF1 is rarely observed." (PMID 30336779, 2018). "Multiple case reports of glomus tumors in patients with NF1 have been reported in the literature." (PMID 37345107, 2023). "Based on previous reports that patients with NF1 may have an increased incidence of glomus tumors, our working hypothesis was that this was such a tumor when the patient was referred." (PMID 30336779, 2018). "No abnormalities in the NF1 gene or Ras-MAPK activation were found in sporadic glomus tumors." (PMID 37345107, 2023).
hamartoma (5 papers, 2012 to 2022). A benign and excessive tumor-like growth of mature cells and normal tissues which grow in a disorganized pattern. "Furthermore, NF1 is associated with hamartomas which were found in two girls with known pathology at time of referral." (PMID 22253792, 2012). "In other words, the development of these tumors and hamartomas seems to be promoted by an Nf1+/− microenvironment." (PMID 30479396, 2018).
head and neck squamous cell carcinoma (5 papers, 2014 to 2021). A squamous cell carcinoma that arises from any of the following anatomic sites: lip and oral cavity, nasal cavity, paranasal sinuses, pharynx, larynx, and salivary glands. "Downregulation of NF1 by microRNA-193b, which is overexpressed in sporadic head and neck squamous cell carcinomas (HNSCC), led to activation of ERK and resulted in tumour progression." (PMID 25026295, 2014). "Interestingly, in head and neck squamous cell carcinoma (HNSCC), miR-193b appears to function as a tumor promoter via negative regulation of the NF1 tumor suppressor, highlighting the pleiotropic action, and context dependence, of microRNAs." (PMID 28542597, 2017).
hereditary tumor syndromes (5 papers, 2016 to 2025). "SOM-NET patients were significantly younger (median age: 55 years; 25th–75th: 44–63) than those with conventional NETs (59 years; 25th–75th: 49.5–70, p = 0.048) and more frequently associated with hereditary tumor syndromes (23% vs 3%, p = 0.029), in particular with NF1." (PMID 35553369, 2022). "Therefore, only the specific phenotypes may guide the clinician in choosing the most accurate genetic test, but the successive testing of genes related to the well-known hereditary tumor syndromes (MEN2, VHL, NF1 and paraganglioma syndromes) would lead to a long and burdensome process." (PMID 34439371, 2021).
insulinomas (5 papers, 2005 to 2025). "Here we report the first case of insulinoma associated with a GIST in a patient not diagnosed with NF-1 as confirmed by the pre-operative endocrine assessment." (PMID 19216788, 2009). "This is the first case report of a pancreatic insulinoma co-existing with a GIST in a patient without NF-1." (PMID 19216788, 2009). "The first important message in our case is that a GIST can occur simultaneously with an insulinoma in the absence of NF-1." (PMID 19216788, 2009).
leiomyosarcoma (5 papers, 2009 to 2024). An uncommon, aggressive malignant smooth muscle neoplasm, usually occurring in post-menopausal women. "However, the literature suggests that the association of NF1 and leiomyomas or leiomyosarcoma is not entirely coincidental." (PMID 19946501, 2009). "The literature suggests, however, that the association of NF1 and leiomyomas or leiomyosarcoma may not be merely coincidental, as documented by various case reports." (PMID 19946501, 2009).
liver cancer (5 papers, 2014 to 2023). An epithelial or non-epithelial malignant neoplasm that arises from the liver. "Unfortunately, however, there is limited research on the role of NF1 in liver cells, so it may be premature to use NF1 as a biomarker for liver cancer treatment." (PMID 36980210, 2023). "Two of these patients had NF1 and the liver cancer was in the field of radiation treatment." (PMID 25452937, 2014).
lung squamous cell carcinomas (5 papers, 2014 to 2023). "Inactivating somatic NF1 mutations were present in 4.0% (108/2696) of the LUAD cases and 6.5% (18/279) of the lung squamous cell carcinomas (LUSC) cases." (PMID 35702826, 2023). "According to the TCGA, somatic NF1 changes are present in approximately 12% of squamous cell lung cancers (SqCC), of which four distinct subtypes have been identified: classical, primitive, basal and secretory expression." (PMID 28637487, 2017). "Approximately 12% of squamous cell lung cancers have alterations in NF1, according to a recently published TCGA study on squamous cell carcinomas." (PMID 25026295, 2014). "The basal expression subtype of squamous cell lung carcinoma characteristically showed alterations in NF1." (PMID 25026295, 2014).
muscular dystrophy (5 papers, 2019 to 2024). Muscular dystrophy (MD) refers to a group of more than 30 genetic diseases characterized by progressive weakness and degeneration of the skeletal muscles that control movement. "The system was implemented in healthy and diseased mouse tissues, including models of muscle myopathy seen with NF1-deficiency in mice and muscular dystrophy caused by dystrophin deficiency." (PMID 34935315, 2021).
neurofibromatosis-Noonan syndrome (5 papers, 2014 to 2023). "Mutations of the NF1 gene are associated with autosomal-dominant NF1 (MedGen UID: 18013), neurofibromatosis-Noonan syndrome (NFNS) (MedGen UID: 419089), and Watson syndrome (MedGen UID: 107817)." (PMID 36629684, 2023). "Neurofibromatosis-Noonan syndrome (NFNS) represents a specific entity in which features of both NS and NF1 can be recognized." (PMID 24767283, 2014). "Previously, we observed an increased prevalence of non-truncating mutations in patients with neurofibromatosis Noonan syndrome (NFNS, MIM #601321), a condition characterized by a clinical phenotype with features overlapping NF1 and NS." (PMID 31487937, 2019).
serous carcinoma (5 papers, 2019 to 2025). "In particular, NF1 alterations, which occurred only in high-grade serous carcinomas in our cohort, are underappreciated as actionable alterations in this histology." (PMID 33947352, 2021). "Regarding NF1 alterations, 14% (n = 5) of high-grade serous carcinoma patients harbored alterations in this gene, whereas no alterations were observed in the other histological subtypes (P = 0.039)." (PMID 33947352, 2021). "The RAS-MAPK signaling pathway (genomic alterations of NF1 at 16% and KRAS at 12% with mutual exclusivity), the PI3K-mTOR pathway (PIK3CA at 12% and TSC2 at 8%), and certain receptor tyrosine kinases (ROS1 at 9% and ERBB2 at 8%) might be candidates for targeted therapy in serous carcinomas." (PMID 38201563, 2023).
spindle cell tumor (5 papers, 2016 to 2025). "Furthermore, any malignant spindle cell tumor in a patient with neurofibromatosis-1 (NF-1) is considered MPNST, unless proven otherwise." (PMID 27872787, 2016).
squamous cell carcinoma (5 papers, 2015 to 2025). A carcinoma arising from squamous epithelial cells. "Exosomal miR-369 derived from cancer-associated fibroblasts promotes squamous carcinoma progression via NF1-mediated MAPK signaling, and it has also been linked to therapeutic resistance in NSCLC." (PMID 41226027, 2025).
anaplastic astrocytoma (4 papers, 2009 to 2023). "One patient had NF1 and the patient with NF1 was treated with 72 Gy (60 fractions) and subsequently developed a histologically proven anaplastic astrocytoma on the edge of the radiotherapy field." (PMID 37519788, 2023). "Two pediatric patients were identified who met criteria for NF1 and had a DMG H3 K27M-mutant (ponto-mesencephalic gliobastoma) and a thalamic anaplastic astrocytoma, H3 K27M-wild type." (PMID 32582540, 2020). "Two anaplastic astrocytomas (AA23 and AA.26) were found to cluster disparately with the PDGF and NF1 groups, respectively." (PMID 19915670, 2009).
aortic aneurysm (4 papers, 2017 to 2022). A ruptured aneurysm located in the wall of the proximal portion of the descending aorta proceeding from the arch of the aorta. "Most aortic aneurysms in NF1 are located in the thoracic descending aorta, but animal models of Nf1 mutant animals demonstrate a strong predisposition for infra-renal AAA as well." (PMID 28116311, 2017). "Similar to persons with NF1, Nf1+/– mice develop robust arterial stenoses and aortic aneurysms and exhibit evidence of chronic inflammation and oxidative stress." (PMID 34934133, 2021). "Endovascular procedure is considered to be feasible and effective for renal artery aneurysms induced by NF-1 by the authors." (PMID 29382000, 2017). "Endovascular procedure is considered to be feasible and effective for renal artery aneurysms induced by NF-1." (PMID 29382000, 2017). "Mutations in the NF1 tumor suppressor gene increase VSMC proliferation and apoptosis, while mice with inactivating mutations in Nf1 develop more frequent and severe aortic aneurysms than mice without the Nf1 mutation." (PMID 28116311, 2017).
Arterial stenosis (4 papers, 2014 to 2022). Narrowing or constriction of the inner surface (lumen) of an artery. "A hallmark of NF1 is the development of early and severe arterial stenosis and aneurysms distributed throughout the arterial network." (PMID 34934133, 2021). "In summary, NF1 is a disorder usually associated with bilateral or unilateral renal artery stenosis." (PMID 24678641, 2014). "In order to specifically target monocytes/macrophages in the natural pathogenesis of arterial stenosis, we performed carotid artery ligation in WT and Nf1+/– mice and provided liposomal clodronate or control liposomes beginning one week after ligation." (PMID 34934133, 2021).
autoimmune disorders (4 papers, 2020 to 2025). "Until a final conclusion on the real incidence of autoimmunity in these syndromes is drawn, pediatricians should be alerted to the possible, although rare, association between AITDs and NS or NF1." (PMID 33557156, 2021).
cardiomyopathy (4 papers, 2021 to 2024). A disease of the heart muscle or myocardium proper. "Several genetic variants have been associated with an increased risk of cardiomyopathy in NS and NF1." (PMID 37529712, 2023). "Cardiomyopathy, a common cardiovascular complication in patients with NS and NF1, is caused by genetic mutations in the RAS-MAPK pathway." (PMID 37529712, 2023). "One potential explanation for the variability in age of onset and clinical penetrance of cardiomyopathy in NS and NF1 is the wide range of genetic mutations that can occur within these genes." (PMID 37529712, 2023). "Also, mutations in the NF1 gene have been associated with a decreased risk of cardiomyopathy." (PMID 37529712, 2023). "The age of onset and clinical penetrance of cardiomyopathy in NS and NF1 are important factors that can influence the diagnosis and management of these conditions." (PMID 37529712, 2023). "The penetrance of cardiomyopathy is also higher in NS than in NF1." (PMID 37529712, 2023). "The age of onset and clinical penetrance of cardiomyopathy differ between NS and NF1." (PMID 37529712, 2023). "For example, proband 30 may have been able to obtain a diagnosis of MYBPC3-associated cardiomyopathy through a comprehensive CHD gene panel but the diagnosis of NF1 would not have been made." (PMID 33888711, 2021).
desmoid tumor (4 papers, 2003 to 2025). A desmoid tumor (DT) is a benign, locally invasive soft tissue tumor associated with a high recurrence rate but with no metastatic potential. "Interestingly, another NF1 patient in our series, who presented with a symptomatic lesion and evidence of edema on MRI, was ultimately diagnosed with a desmoid-type fibromatosis." (PMID 41002920, 2025).
diabetes (4 papers, 2013 to 2022). "In case of NF1-associated somatostatin-related symptoms, management is not well defined and can include treatment of diabetes, cholecystectomy, and pancreatic enzyme supplementation." (PMID 34025587, 2021). "Twelve pathways show a nominally significant result: Focal junction assembly, cleavage of lamina in apoptosis, systemic lupus erythematosus, glycan catabolism, TGFi, OA transport, fatty acid biosynthesis, NF-1, Myc Mad Max, type 1 diabetes mellitus, and triacylglycerols degradation." (PMID 27980659, 2016). "Here, we report a case with established NF1 who also had a diagnosis of diabetes mellitus." (PMID 24286013, 2013). "Here, we report a case with established NF1 who also has a diagnosis with diabetes mellitus." (PMID 24286013, 2013).
encephalitis (4 papers, 2021 to 2025). An acute inflammatory process affecting the brain parenchyma. "In silico analysis revealed the presence of binding sites for a putative TF nuclear factor-1 (NF-1) in its LTRs; NF-1 likely activates BoRV CH15 expression, damaging the brain neurons and causing cattle encephalitis." (PMID 38540701, 2024). "One case showed an exceptional association of NF1 and anti-NMDAR encephalitis." (PMID 34056010, 2021).